OVOS2P (ovostatin 2, pseudogene)
Synonyms: DKFZp686C0338; DKFZp434C0631; OVOS2
Gene: Transcribed unprocessed pseudogene on chromosome 12 (31,112,236 to 31,201,235, reverse strand). Ensembl gene ENSG00000177359.
Diseases named in the same sentence as OVOS2P in open-access papers:
OVOS2P is named in the same sentence as 6 diseases in open-access papers, as found by Europe PMC text mining. Sharing a sentence is not in itself a finding about the gene and the disease.
OVOS2P shares sentences with these, for which no sentence is quoted: melanoma (2 papers); tumor (2); cancer (1); carcinoid (1); germ cell tumor (1); ovarian carcinoma (1).